DNAJC21 (DnaJ heat shock protein family (Hsp40) member C21)
Description:
May act as a co-chaperone for HSP70. May play a role in ribosomal RNA (rRNA) biogenesis, possibly in the maturation of the 60S subunit. Binds the precursor 45S rRNA.
Synonyms: DNAJA5; GS3; JJJ1; BMFS3
Tractability: PROTAC: ubiquitination databases record sites on it; its protein half-life has been measured.
Gene: Protein-coding gene on chromosome 5 (34,929,548 to 34,958,964, forward strand). Ensembl gene ENSG00000168724.
Subcellular location: Cytoplasm; Nucleus; Nucleus, nucleolus
Subcellular location (Human Protein Atlas): Cytosol; Nucleoli
Gene Ontology:
Molecular function: protein binding; RNA binding; nucleic acid binding; zinc ion binding
Biological process: protein folding
Cellular component: cytoplasm; cytosol; nucleolus; nucleus; ribosome
Genetic constraint (gnomAD): Loss-of-function variants: 55 observed, 63.55 expected, observed/expected ratio (o/e) 0.87, 90% interval 0.7 to 1.08. The upper end of that interval is the gene's LOEUF score, 1.08, which puts it in group 4 of 6, group 1 being the genes least tolerant of losing a copy. Missense variants: 555 observed, 575.12 expected, observed/expected ratio (o/e) 0.97, 90% interval 0.9 to 1.03. Synonymous variants: 186 observed, 193.28 expected, observed/expected ratio (o/e) 0.96, 90% interval 0.85 to 1.09.
Gene-disease validity (ClinGen):
ClinGen rates the evidence that DNAJC21 causes each of these diseases.
bone marrow failure syndrome 3 (autosomal recessive): Definitive.
Homologues: Orthologues: chimpanzee DNAJC21 (99% identical), macaque DNAJC21 (98% identical), dog DNAJC21 (92% identical), rabbit DNAJC21 (92% identical), rat Dnajc21 (85% identical), mouse Dnajc21 (85% identical), zebrafish dnajc21 (64% identical), tropical clawed frog dnajc21 (55% identical), Drosophila melanogaster CG2790 (41% identical), Caenorhabditis elegans dnj-17 (37% identical), Drosophila melanogaster l(3)80Fg (14% identical), Caenorhabditis elegans dnj-8 (13% identical), and 8 more. Paralogues in human: DNAJC13 (20% identical), DNAJC16 (17% identical), DNAJC2 (17% identical), DNAJC11 (16% identical), DNAJC10 (15% identical), DNAJC18 (15% identical), DNAJC1 (13% identical), DNAJC17 (12% identical), DNAJC5 (12% identical), DNAJC5B (12% identical), DNAJC3 (11% identical), DNAJC5G (11% identical), and 8 more.
Diseases named in the same sentence as DNAJC21 in open-access papers:
DNAJC21 is named in the same sentence as 15 diseases in open-access papers, as found by Europe PMC text mining. Sharing a sentence is not in itself a finding about the gene and the disease. The quoted sentences say what the papers report.
Fanconi anemia (1 paper, 2020). Fanconi anemia (FA) is a hereditary DNA repair disorder characterized by progressive pancytopenia with bone marrow failure, variable congenital malformations and predisposition to develop hematological or solid tumors. "Further disorders include Fanconi anemia and rare entities, including mutations in DNAJC21 and ERCC6L2." (PMID 33097095, 2020).
liver cancer (1 paper, 2021). An epithelial or non-epithelial malignant neoplasm that arises from the liver. "Several homologs of the Hsp40/DnaJ protein family (DnaJB6, DnaJC1, DnaJC5, DnaJC7, and DnaJC21) have been identified as unfavorable prognostic markers in liver cancer." (PMID 34356495, 2021).
liver cirrhosis (1 paper, 2021). "Furthermore, other members of the DnaJ protein family have been assigned roles in other liver pathologies, such as steatosis development for DnajC7 and liver cirrhosis for DnajC21." (PMID 34356495, 2021).
retinitis pigmentosa (1 paper, 2018). Retinitis pigmentosa (RP) is an inherited retinal dystrophy leading to progressive loss of the photoreceptors and retinal pigment epithelium and resulting in blindness usually after several decades. "Interestingly, retinitis pigmentosa was associated with several other hereditary bone marrow failure disorders, including DNAJC21‐related Shwachman‐Diamond syndrome and Revesz syndrome." (PMID 29633571, 2018).
infection (1 paper, 2014). The state of being infected such as from the introduction of a foreign agent such as serum, vaccine, antigenic substance or organism. "For instance, Dnajb9L2, Dnajb11, Dnajb12b, Dnajc3, Dnajc20, Dnajc21, and Dnajc29 were up-regulated at only one time point (1.5× fold change cutoff); similarly, Dnajb13 was only down regulated at 24h after infection." (PMID 25542027, 2014).
DNAJC21 also shares sentences with these, for which no sentence is quoted: tumor (2 papers); breast carcinoma (1); cancer (1); chronic granulomatous disease (1); Congenital neutropenia (1); epilepsy (1); hematologic malignancies (1); pancreatic cancer (1); Revesz syndrome (1); steatosis (1).